ZDHHC11B (zDHHC palmitoyltransferase 11B (putative))
Description:
Probable palmitoyltransferase that could catalyze the addition of palmitate onto various protein substrates and be involved in a variety of cellular processes (By similarity). May play a role in cell proliferation.
Synonyms: DHHC-11B
Tractability: Antibody: UniProt predicts a signal peptide or a membrane-spanning region.
Gene: Protein-coding gene on chromosome 5 (710,355 to 784,729, reverse strand). Ensembl gene ENSG00000206077.
Subcellular location: Membrane
Subcellular location (Human Protein Atlas): Golgi apparatus
Gene Ontology:
Molecular function: protein-cysteine S-palmitoyltransferase activity; palmitoyltransferase activity
Biological process: antiviral innate immune response; protein targeting to membrane
Cellular component: endoplasmic reticulum; membrane
Genetic constraint (gnomAD): Loss-of-function variants: 15 observed, 22.81 expected, observed/expected ratio (o/e) 0.66, 90% interval 0.44 to 1.01. The upper end of that interval is the gene's LOEUF score, 1.01, which puts it in group 4 of 6, group 1 being the genes least tolerant of losing a copy. Missense variants: 234 observed, 244.74 expected, observed/expected ratio (o/e) 0.96, 90% interval 0.86 to 1.07. Synonymous variants: 117 observed, 100.77 expected, observed/expected ratio (o/e) 1.16, 90% interval 1 to 1.35.
Homologues: Orthologues: rat Zdhhc11 (48% identical), mouse Zdhhc11 (46% identical), zebrafish zdhhc11 (25% identical), Caenorhabditis elegans dhhc-2 (14% identical), Caenorhabditis elegans dhhc-9 (14% identical), Caenorhabditis elegans dhhc-12 (13% identical), Caenorhabditis elegans dhhc-4 (12% identical), Caenorhabditis elegans dhhc-7 (11% identical), Drosophila melanogaster CG1407 (11% identical), Drosophila melanogaster CG17287 (11% identical), Caenorhabditis elegans dhhc-5 (11% identical), Drosophila melanogaster Dnz1 (11% identical). Paralogues in human: ZDHHC11 (92% identical), ZDHHC1 (37% identical), ZDHHC14 (16% identical), ZDHHC3 (15% identical), ZDHHC4 (15% identical), ZDHHC7 (15% identical), ZDHHC19 (15% identical), ZDHHC23 (15% identical), ZDHHC18 (14% identical), ZDHHC9 (14% identical), ZDHHC12 (14% identical), ZDHHC2 (13% identical), and 5 more.
Diseases named in the same sentence as ZDHHC11B in open-access papers:
ZDHHC11B is named in the same sentence as 8 diseases in open-access papers, as found by Europe PMC text mining. Sharing a sentence is not in itself a finding about the gene and the disease. The quoted sentences say what the papers report.
Burkitt lymphoma (3 papers, 2021 to 2023). A rare form of malignant mature B-cell non-Hodgkin lymphoma. "Previous studies have indicated that ZDHHC11 and ZDHHC11B play critical roles in maintaining the oncogenic MYC-miR-150-MYB axis in Burkitt’s lymphoma, and ZDHHC11 may be a biomarker to identify high-risk bladder cancer patients with disease progression." (PMID 34490261, 2021). "ZDHHC11B (Zinc Finger DHHC-Type Containing 11B) is involved in a network that promotes the proliferation of Burkitt lymphoma cells." (PMID 37403156, 2023). "Research in Burkitt lymphoma demonstrated a MYC-miR-150-ZDHHC11/B-MYB network, in which high levels of MYC repress miR-150, which leads to derepression of MYB, ZDHHC11 and ZDHHC11B, and promotes proliferation." (PMID 33593440, 2021).
lung adenocarcinoma (2 papers, 2023 to 2025). A carcinoma that arises from the lung and is characterized by the presence of malignant glandular epithelial cells. "ZDHHC11B up-regulation was observed to significantly inhibit the growth of lung adenocarcinoma in a mouse xenograft model." (PMID 39901294, 2025). "The role and mechanism of zinc finger DHHC protein 11B (ZDHHC11B) in lung adenocarcinoma (LUAD) remain unclear." (PMID 37434393, 2023).
hepatoblastoma (1 paper, 2023). Hepatoblastoma (HB) is a malignant hepatic tumor and is the most common pediatric liver cancer. "The CNV of ZDHHC11 and ZDHHC11B are associated with hepatoblastoma and primary open-angle glaucoma." (PMID 37403156, 2023).
pancreatic cancer (1 paper, 2024). "Among them, only ZDHHC11B was previously associated with pancreatic cancer risk." (PMID 39408606, 2024).
tumor (3 papers, 2022 to 2025). "We constructed a stable overexpression cell model and conducted functional experiments that identified inhibitory factors for tumor cell growth associated with a high expression of ZDHHC11B." (PMID 37434393, 2023). "Among them, ARL14 was significantly upregulated in tumor samples, while ZDHHC11B and HLF were downregulated." (PMID 39901294, 2025). "As expected, ARL14 was significantly up-regulated in tumor samples, while ZDHHC11B and HLF were clearly down-regulated in tumor." (PMID 39901294, 2025). "Our study is the first to show that sustained low expression of ZDHHC11B in LUAD reduces the onset of EMT in tumor cells and inhibits tumor growth effectively." (PMID 37434393, 2023). "To assess the in vivo function of ZDHHC11B, we employed a model of subcutaneous tumor in nude mice for our study." (PMID 37434393, 2023). "We observed that the rate of tumor growth was slower in the group in which ZDHHC11B was upregulated than in the control group." (PMID 37434393, 2023). "In summary, ZDHHC11B may act as a tumor suppressor gene in LUAD." (PMID 37434393, 2023). "In training set (TCGA), ZDHHC11B and HLF were significantly downregulated in tumor samples, whereas ARL14 was significantly upregulated (P < 0.05)." (PMID 39901294, 2025). "ZDHHC11B has been described as an oncogene that promotes cell proliferation, while TARP also promotes tumor cell invasion." (PMID 35562926, 2022).
cancer (1 paper, 2023). A tumor composed of atypical neoplastic, often pleomorphic cells that invade other tissues. "Further research is needed to investigate the specific roles of ZDHHC11B and other ZDHHC family members in the regulation of palmitoylation and EMT markers in cancer, as well as their potential as therapeutic targets." (PMID 37434393, 2023). "However, there is no direct evidence linking ZDHHC11B to the palmitoylation of EMT markers in cancer." (PMID 37434393, 2023).
ZDHHC11B also shares sentences with these, for which no sentence is quoted: bladder cancer (1 paper); primary open-angle glaucoma (1).